IL6 (interleukin 6)
Diseases named in the same sentence as IL6 in open-access papers (continued):
Sharing a sentence is not in itself a finding about the gene and the disease.
cancer (continued). "Golgin-97 facilitates Golgi tethering and vesicle formation for cytokines, including IL-10 and IL-6, which alters the cancer secretome during metastasis." (PMID 35563790, 2022). "Our previous study showed that mitochondrial Lon upregulation increases IL-6 expression and promotes cancer progression and metastasis." (PMID 35296653, 2022). "IL-6 secreted from CUL4B-dificient MDSCs enhances the stem cell-like properties in cancer cells through IL-6/STAT3 pathway." (PMID 36439186, 2022). "NF-κB pathway was similarly evoked in the liver, WAT, and skeletal muscle, triggering inflammation cascade in cancer cachexia via IL-1β, IL-6, and IL-8, etc.." (PMID 36581870, 2022). "CAFs increased the secretion of cancer-promoting cytokines, including interleukin-6, and gained resistance to chemotherapy relative to NGFs." (PMID 35615263, 2022). "Activated macrophages released large amounts of inflammatory cytokines, e.g., COX-2, TNF-α, IL-6 and plasminogen activator inhibitor-1 (PAI-1), aggravating the state of chronic inflammation and enhancing insulin resistance and the risk of cancer initiation." (PMID 35328822, 2022). "IL-6/STAT3 activation also induces cancer stem cell (CSC) formation in metastatic lesions, which promotes therapeutic resistance." (PMID 35020853, 2022). "Proinflammatory cytokines, such as interleukin–6 (IL–6), interleukin–1, and tumor necrosis factor–alpha, are secreted by monocytes or macrophages under inflammatory conditions and cancer." (PMID 34980029, 2022). "Accumulating evidence has proved the significance of senescent cells in the microenvironment of cancer cells, of which pro-inflammatory IL-6 and IL-8 are consistently present." (PMID 35924148, 2022). "CAFs isolated from metastatic BC also express IL-6 which promotes tumor growth and invasiveness through paracrine induction of Notch in cancer cells." (PMID 35682974, 2022). "Previous reports indicate that IL-6, IL-8, or TNF-α are produced in excess in patients with IBD or cancer, and increased levels of these cytokines are associated with disease progression." (PMID 35739324, 2022). "As reported by a previous study, fat cells, once activated by cancer cells, will eventually secrete higher levels of pro-inflammatory cytokines (e.g., IL-6)." (PMID 36106333, 2022). "Activated NF-κB in HCC cells has been found to promote the expressions of inflammatory cytokines (e.g., IL-6, IL-1β), which creates a cancer-promoting inflammatory microenvironment and is involved in the carcinogenesis and progression of HCC." (PMID 36260873, 2022). "Several IL-6 inhibitors are already approved for immune disorders and are being investigated for their role in anti-cancer therapy." (PMID 35159126, 2022). "HCV infection promotes IR through the insulin signaling pathway in hepatocytes and lead to a rise in levels of tumor necrosis factor and interleukin-6, which aid the advancement of liver steatosis and inflammation and subsequent cancer." (PMID 36115934, 2022). "Nevertheless, higher expression of IL-32α has been found to activate NF-κB and STAT3 pathways and induce the production of IL-6, thus supporting the cancer proliferation and progression in MM patients." (PMID 35281008, 2022). "It is reported that high expression of IL-6 hads been seen in many types of cancer and it functioned as a poor prognostic factor." (PMID 35550592, 2022). "Conversely, NF-κB and JAK/STAT3 pathways also contribute to the production of IL-6, forming a cancer-associated NF-κB/IL-6/STAT3 positive feedback loop, making cancer a de facto chronic inflammatory disease." (PMID 35884974, 2022). "In summary, the structure motif of bis-pentamethinium salts represents a promising starting point for the design of novel multitargeting compounds with the potential to inhibit IL-6 signaling and simultaneously target mitochondrial metabolism in cancer cells." (PMID 36015338, 2022).
cancer (continued). "The use of IL-6 blockers as anti-cancer agents has been evaluated in many cancers (i.e., lung, prostate cancers, OC, B-cell NHLS, renal cell carcinoma)." (PMID 36140335, 2022). "Dysregulated inflammatory responses in certain infectious/inflammatory diseases and cancers are characterised by inappropriate levels of IL-6, the speed of their generation and their major site of production, such as a vital organ." (PMID 35928820, 2022). "The cytokine IL-6 is involved not only in cancer inflammation but also in hematopoiesis, bone metabolism and embryonic development." (PMID 36611932, 2022). "It has been proven that as a result of the elimination of senescent cells, the level of proinflammatory cytokines, such as IL-1α, IL-6, and tumor necrosis factor α (TNFα), decreases, which prevents cancer relapse." (PMID 36232388, 2022). "The IL-6/JAK/STAT3 regulatory axis interleukin-6 (IL-6) plays a central role in the pathogenesis of several cancers, including MM." (PMID 35326392, 2022). "IL-6 was identified as a mediator for the cross-talk between bone marrow and cancer cells, and the levels of IL-6 correlated with MDP growth and increased incidence of metastasis." (PMID 36429126, 2022). "Activation of IL-6/JAK2/STAT3 pathway is closely associated with EMT and stem cell-like features, ultimately leading to poor prognosis in patients with various cancers." (PMID 36591515, 2022). "Interactions of CAFs with cancer cells additionally results in a dramatic increase in IL-6 production in vitro." (PMID 35479076, 2022). "Many studies have reported that IL-6 is highly upregulated in several types of cancers and is considered one of the most important cytokines during cancer development and metastasis." (PMID 35361764, 2022). "IL6 was particularly upregulated in murine cancer cells, while OAS1 was significantly upregulated by human cancer cells." (PMID 35937459, 2022). "Cancer-associated adipocytes (CAA) are characterized by a smaller size, they secrete more chemokine ligand 2 and 5 (CCL2, CCL5), IL-1β, IL-6, leptin, VEGF and TNF-α, but lower the expression of adiponectin." (PMID 35741450, 2022). "The results reveal a strong connection between adipocytes, IL6, and the cancer population, suggesting them as potential targets for therapies." (PMID 35294447, 2022). "As for parameters 7 and 8, we refer to the ODE paper for a detailed discussion about the importance of adipocytes and IL6 in cancer therapy." (PMID 35629230, 2022). "IL-6 induces C-reactive protein production and affects cancer cell proliferation, invasion, metastasis, angiogenesis, and resistance to treatment via the JAK/STAT3 pathway." (PMID 36294421, 2022). "The antibody efficiently inhibits the EGFR associated signal transduction, prevents proliferation, arrests the cell cycle in the G1 phase and decreases interleukin 6 (IL-6) secretion by the cancer cells." (PMID 35937253, 2022). "Of note, higher levels of inflammatory (IL-6, hs-CRP) and coagulation (D-dimer) markers are associated with an increased risk of cardiovascular disease (CVD), cancer, and all-cause mortality." (PMID 35359950, 2022). "The amount of IL-6 in the circulating blood reflects the cancer state and when IL-6 is elevated, CRP is increased and albumin is decreased." (PMID 36260237, 2022). "Ιt is noteworthy that Interleukin (IL)-6, the founding member of myokines, acts in a pleiotropic manner regarding cancer evolution, since different origins and signaling pathways have been associated with either its anti- or pro-tumorigenic properties." (PMID 35454797, 2022). "As a result of several large-scale studies, the serum level of IL-6 was suggested as a reliable general marker of inflammaging and some specific diseases and infections like COVID-19 and cancer." (PMID 35163247, 2022).
cancer (continued). "A study using an in vitro co-cultured system demonstrated that nab-PTX inhibited CAF-induced cancer cell migration, invasion, and EMT phenotype by increasing the expression of CXCL10 in cancer cells to counteract the effect of IL-6 secreted by CAFs." (PMID 35327514, 2022). "In other cancers, exosomes have been found to induce IL-6 production in monocytes through a Toll-like receptor (TLR)." (PMID 36741380, 2022). "High levels of IL-6 correlate to cancer metastasis, while high IL-6 and IL-17 predict cancer recurrence after radical treatments." (PMID 36428939, 2022). "In the same way, the stimulation of IL-6 drives epigenetic changes dependent on NF-κB and DNA methyltransferases that resulted in epigenetic reprogramming and the emergence of cancer stem cells." (PMID 35806442, 2022). "This CD90-dependent bound leads to the production of cytokines such as IL-6, IL-8, GM-CSF by cancer stem cells which further support cancer stemness." (PMID 35309358, 2022). "It is worth noting that in the same paper, the authors reported that BAG3 knockdown in cancer cells favors the recruitment of Argonaute 2 (Ago2) to IL‐6 mRNA, which results in the IL‐6 mRNA destabilization and finally in the reduction of fibrosis onset." (PMID 34741483, 2022). "As a pleiotropic cytokine with diverse systemic roles, IL-6 plays a crucial role in inflammatory processes, including immunological diseases and cancers." (PMID 36140470, 2022). "Overall, data have shown that IL-6 prepares cancer stem cells, likely via a chemotactic mechanism, for the epithelial-to-mesenchymal transition (EMT), essential for the next step of the invasion-metastasis cascade." (PMID 36429126, 2022). "The IL-6 signalling pathway plays a significant role in cancer biology, particularly in its involvement in metastasis formation." (PMID 36429126, 2022). "Simultaneously, IL-6 also prompts cancer immune escape by recruiting immunosuppressive cells into the TME." (PMID 35967313, 2022). "Inhibition of IL-6 and its signalling pathways is an intensively studied therapeutic approach in cancer treatment." (PMID 36429126, 2022). "Regarding comparison of the salivary cytokines between cancer patients before radiotherapy and the control group, we only found significant differences in the IL-6 levels, which were higher in the cancer group (Mann–Whitney U test = 241; p < 0.01)." (PMID 34251535, 2022). "NF-kB is constitutively active in many cancers and aids in the secretion of leptin, pro-inflammatory cells and cytokines like interleukins-1β (IL-1β) and interleukin 6 (IL-6)." (PMID 35832545, 2022). "This means that other infiltrating stromal and immune cells were a source of IL-6; our goal, herein, was strictly to eliminate cancer-cell-derived IL-6." (PMID 36142210, 2022). "IL6 plays a central role in inflammatory and cancer promotion of HNSCC and is considered as a promising therapeutic target." (PMID 34850540, 2022). "Among them, we identified IL-6 as a proinflammatory cytokine that mediates the activation of Stat-3 in cancer cells, thus promoting tumorigenesis." (PMID 35625629, 2022). "IL6 is involved in the formation of mammary globules enriched with stem cell-like cancer cells and progenitor cells." (PMID 36591515, 2022). "Protection of cancer cells by IL-6 from apoptosis and inflammation, DNA damage, antiproliferative, antimetastatic, and antiangiogenic gains of chemotherapy is considered as a major cause of cytotoxic drugs resistance." (PMID 35269343, 2022). "At the same time, EBV can also release inflammatory factors, such as IL6, IL-10 and leptin, which promote fat consumption and help cancer cells to evade immune surveillance." (PMID 36185215, 2022). "IL-6 is a cytokine that plays an important role in cancer progression, and treatments that inhibit IL-6 signalling are expected to have a beneficial effect in lymphoid malignancies, as well as in patients with solid tumours, including PCa." (PMID 36009554, 2022).
cancer (continued). "After adipocytes are reprogrammed into cancer-associated adipocytes by an EOC-derived mediator, these activated adipocytes can release various adipokines, such as IL-6, IL-8, MCP-1, and TIMP-1 that contribute to building the omental metastatic niche for EOC." (PMID 35563509, 2022). "Activation of the MAPK and NF-kB pathways causes the release of proinflammatory cytokines, such as interleukin-6 (IL-6), IL-8, and tumor necrosis factor-a (TNF-a), which leads to the inflammatory response, and eventually causes cancer." (PMID 36289913, 2022). "IL-6 has evident pleiotropic effects in hematopoiesis, inflammation, the immune response, and cancer." (PMID 36072935, 2022). "IL-6, IL-8 and VEGF are largely secreted also by cancer-associated fibroblasts (CAFs), the most heterogeneous population of stromal cells in the BC microenvironment." (PMID 36358839, 2022). "In all samples, α-SMA and FAP (as known CAF markers) and interleukin-6 (IL-6) were highly expressed in the fibroblasts surrounding cancer cells." (PMID 35615263, 2022). "Analogously, extensive studies regarding the role of TA-MSCs in building cancer-associated vasculature largely concentrate on pro-angiogenic chemokines or growth factors such as VEGF, IL-6, and the CXCL12/CXCR4 axis." (PMID 36324128, 2022). "Certain cancer cell lines (such as the T24 bladder carcinoma) constitutively produce high levels of IL-6." (PMID 35406728, 2022). "Vitamin B6 levels decrease with increasing levels of inflammatory markers such as interleukin-6, C-reactive protein, and the alpha tumor necrosis factor which are involved in cancer." (PMID 35399658, 2022). "BMI1 expression can be increased by IL6 secreted by endothelial cells and by cisplatin treatment through the induction of IL6 expression by the cancer cells themselves." (PMID 35159370, 2022). "IL-6 is one of the candidates that can cooperate with TNFα or act alone as a mediator of systemic inflammation in cancer cachexia." (PMID 36078078, 2022). "Treatment of anti-VEGF therapy-induced cancer cell necrosis in adipocyte-poor regions while adipocyte-rich regions remained viable, attributed to increased pro-inflammatory molecule IL-6." (PMID 35186923, 2022). "IL‐6 is a pleiotropic and multi‐tasking cytokine with a pro‐ or anti‐inflammatory activity that is produced in chronic inflammatory conditions and cancer." (PMID 35301813, 2022). "In cancer patients, cytokine circulating levels, particularly IL-6, have been positively correlated with scores of cognition and somatic fatigue." (PMID 36139563, 2022). "MyCAFs are highly expressed in αSMA and located adjacent to cancer cells, while iCAFs secrete inflammatory mediators such as interleukin‐6 (IL‐6) and are located far away from cancer cells." (PMID 35603909, 2022). "They primarily target fibroblasts and turn them into cancer-associated fibroblasts, which secrete high amounts of TGF-β, IL-6." (PMID 35159299, 2022). "Cancer patients have chronically increased Interleukin-6 (IL-6) in the circulating blood, affecting the acute-phase proteins (APPs); positive APP corresponds to CRP, and negative APP to albumin." (PMID 35204642, 2022). "Multiple cancer types secrete IL-6 and this can be amplified by host-derived proinflammatory cytokines (e.g., IL-1)." (PMID 36078078, 2022). "Many cancer cells produce a lot of interleukin-6 (IL-6) and signal transducer activator of transcription 3 (STAT3)." (PMID 37829248, 2022). "Cancer-induced changes in circulating factors, such as IL-6 and tumor necrosis factor-α (TNF-α), contribute to increased adipose lipolysis in CAC, possibly through modulating ATGL." (PMID 35684106, 2022). "It has been demonstrated that IL-6 is capable of the EMT process induction in various types of cancer." (PMID 35361764, 2022). "A systematic review of 34 studies showed that IL-6 and TNF were associated with the severity of oral mucosal tissue damage in patients with cancer; the most investigated cytokines were IL-6, TNF, and IL-10." (PMID 35476641, 2022).
cancer (continued). "IL-6 is found to be elevated in a majority of cancers and involved in the malignant progression of cancers." (PMID 35194188, 2022). "Some limitations of targeting cGAS/STING in cancer exist, including evidence of cGAS/STING silencing or loss-of-function mutations in certain tumors and cGAS/STING-driven IL-6-dependent survival of chromosomally instable cancers." (PMID 36276148, 2022). "IL-6 has been reported to contribute to inflammation and fibrosis, and to regulate the immune system and activate cancer-related signal transduction pathways, such as NF-κB and STAT3." (PMID 35277009, 2022). "In a review paper, the IL-6 serum level at diagnosis was, e.g., significantly correlated to survival in 82/101 series comprising 9917 out of 11,583 patients with 23 different cancer types." (PMID 35326661, 2022). "Secretion of IL-6 and other cytokines including IL-11 function by promoting stemness and survival cues to cancer cells and subsequent persistence after cisplatin treatment." (PMID 35159370, 2022). "It was found that the levels of D-dimer, FDP, CRP and IL-6 in cancer patients were significantly higher than those in the COVID-19 cohort." (PMID 36439504, 2022). "The PI3K/AKT/mTOR pathway, which plays an important role in survival and proliferation of cancer cells, is also activated by IL-6." (PMID 35470375, 2022). "Proinflammatory cytokines, TNF-α and IL-6, mediate the augmented muscle protein degradation in cancer." (PMID 35736478, 2022). "Resveratrol was reported to decrease CAF pro-tumorigenic factor IL-6 and inhibit cancer cell EMT and migration in cholangiocarcinoma." (PMID 35327514, 2022). "As shown in these articles, IL-6 participates in the control of the low level of differentiation of cancer cells and the regulation of their migratory activity." (PMID 35055153, 2022). "Several studies also demonstrated that high circulating IL-6 and YKL-40 levels in patients with different types of cancer, including PDAC, are associated with poor prognosis." (PMID 35335885, 2022). "Another important consideration is that cytokines, such as interleukin-1, interleukin-6, and tumor necrosis factor-α, inhibit the synthesis of albumin, and the levels of these cytokines are increased in patients with malignant tumors." (PMID 36316884, 2022). "Cancer triggers systemic inflammation with a corresponding increase in pro-inflammatory cytokines such as interleukin 6 (IL6) and tumor necrosis factor α (TNFα)." (PMID 35327399, 2022). "After being modified by the phosphorylation, the activated TF JDP2 would upregulate the DNA-methylated target gene IL6, which leads to promoting cell apoptosis and immune response against cancer." (PMID 35743172, 2022). "Tocilizumab, an antibody that competitively inhibits the binding of IL-6 to its receptor (IL-6R), is already used by oncologists to reduce pulmonary distress in cancer patients during immune checkpoint inhibitors." (PMID 36362770, 2022). "IL-6 is a pleiotropic cytokine that plays a major role in angiogenesis, cancer cell survival, chemotherapy resistance, and the development of liver metastases." (PMID 35335885, 2022). "Paclitaxel, a microtubule poison, induces apoptosis of cancer cells and activates IL-1β, IL-8, IL-6, thus, enhancing pro-tumorigenic inflammation." (PMID 36611932, 2022). "Interleukin 6 has been demonstrated to be a pleiotropic cytokine in the regulation of cancer progression, and it is involved in EMT, CSCs, angiogenesis, and therapeutic resistance." (PMID 34991668, 2022). "Among those downregulated, CXCL1, CCL2, CXCL8, CTGF, LIF, and IL-6 are known to be involved in fibrosis or cancer stroma." (PMID 36289649, 2022). "In the transcriptional level, cancer related cytokines including IL-1β, IL-6 and TNF-α were all reduced after IVM treatment." (PMID 36132145, 2022). "Elevated levels of IL-6 have been shown to promote cancer cell proliferation, angiogenesis and metastasis." (PMID 35022523, 2022).